ENSG00000284393 (novel protein)
Gene: Protein-coding gene on chromosome 12 (8,138,140 to 8,175,320, forward strand). Ensembl gene ENSG00000284393.
Genetic constraint (gnomAD): Missense variants: 70 observed, 84.31 expected, observed/expected ratio (o/e) 0.83, 90% interval 0.68 to 1.01. Synonymous variants: 22 observed, 26.7 expected, observed/expected ratio (o/e) 0.82, 90% interval 0.59 to 1.18.